SOX6 (SRY-box transcription factor 6)
Diseases named in the same sentence as SOX6 in open-access papers (continued):
Sharing a sentence is not in itself a finding about the gene and the disease.
neuroblastoma (4 papers, 2019 to 2024). Neuroblastoma (NB) is the most common solid, extracranial childhood tumor. "In neuroblastoma, the subset of cells expressing SOX6 shows minimal overlap with those expressing LIN28B, supporting a SOX6 mediated LIN28B downregulation in this context." (PMID 38704454, 2024). "Metformin significantly decreased Cdk5 and increased Sox6 during cell differentiation and promoted neuronal differentiation via crosstalk between Cdk5 and SOX6 in neuroblastoma cells." (PMID 36614288, 2023). "We therefore assessed the effect of SOX6 overexpression in human neuroblastoma SH-SY5Y cells." (PMID 38704454, 2024). "First we show that LIN28B and Sox6 expression is mutually exclusive in mouse and human erythropoiesis, which represents a well-defined model of development as well in several cancer cells, in particular neuroblastoma and hepatocarcinoma cell lines." (PMID 38704454, 2024). "In addition, in neuroblastoma cell lines, SOX6 and LIN28B expression negatively correlate." (PMID 38704454, 2024). "We find that the repression of LIN28B by SOX6 also occurs in tumor cell types representative of other tissues, such as SH-SY5Y neuroblastoma and HepG2 hepatoblastoma cells, where LIN28B is highly expressed." (PMID 38704454, 2024). "The generally high but variable expression of SOX6 was also observed in EwS cell line models compared to cell lines of three other pediatric cancer types including osteosarcoma (U2OS and SAOS-2), neuroblastoma (TGW and SK-N-AS) and rhabdomyosarcoma (Rh36 and Rh4)." (PMID 32415069, 2020).
Sepsis (4 papers, 2022 to 2025). Sepsis is defined as life-threatening organ dysfunction caused by a dysregulated host response to infection. "Based on computer analysis, a recent study verified the mechanism of action of Circ_000149 through cell models and animal models of lung injury caused by sepsis, providing a new idea for the targeted regulation of SOX6." (PMID 40585335, 2025). "miR-21, miR-499, and miR-155 were shown to regulate IL-12, target SRY box 6 (SOX6) gene to influence sepsis-related lung deterioration, and down-regulate SHIP1 and SOCS1, respectively." (PMID 39434774, 2024). "miR-499-5p can mitigate pulmonary fibrosis in mice with sepsis-induced lung injury by targeting Sry-related high-mobility-group box 6 (SOX6)." (PMID 37197357, 2023). "Although research illustrating the effects of miR-499-5p in atrial fibrosis is limited, among other fibrosis, restoring miR-499-5p decreases collagen fibers and pulmonary fibrosis degree in sepsis-induced lung injury mice by depleting SOX6." (PMID 37197357, 2023).
cardiomyopathy (3 papers, 2020 to 2024). A disease of the heart muscle or myocardium proper. "SOX6, regulated by miRNAs, is a pivotal mediator in adult tissue regeneration, homeostasis, and physiology, and aberrant expression of SOX6 is implicated in diverse diseases, including cardiomyopathy." (PMID 37197357, 2023). "They showed cardiac specific Trbp KO mice express lower miR‐208a and overexpress Sox6 that result into progressive cardiomyopathy and lethal heart failure." (PMID 33230925, 2020). "Several studies suggested that differential expression of SOX6 may account for numerous diseases, such as cardiomyopathy." (PMID 39379100, 2024).
chondrosarcoma (3 papers, 2010 to 2024). A malignant cartilaginous matrix-producing mesenchymal neoplasm arising from the bone and soft tissue. "Besides this, Liu and Lefebvre found that the regulatory trio of SOX9, SOX5 and SOX6 cooperatively work together to activate super-enhancers in a genome-wide way in rat chondrosarcoma cells." (PMID 26927636, 2016). "As chromatin source for ChIP-on-chip experiments, we used rat chondrosarcoma cells (RCS cells), because these cells display many chondrogenic characteristics including secretion of specific cartilage ECM proteins and high contents of SOX9, SOX5 and SOX6." (PMID 20404928, 2010).
esophageal cancer (3 papers, 2016 to 2022). A primary or metastatic malignant neoplasm involving the esophagus. "SOX6 acts as a tumor suppressor in esophageal cancer and is an independent prognostic factor of esophageal cancer." (PMID 31729835, 2020).
glioblastoma (3 papers, 2020 to 2022). The most malignant astrocytic tumor (WHO grade IV). "MAGE-E1 and SOX-6 expression were associated with lower Kps score and lower survival rate, which indicates their possible importance in determination of prognosis in glioblastoma." (PMID 33936223, 2021). "The level of expression of all the three CT antigens, especially MAGE-E1 and SOX-6, were high in patients with glioblastoma." (PMID 33936223, 2021). "MAGE-E1 and SOX-6 can be considered as important markers in determining the prognosis of glioblastoma." (PMID 33936223, 2021). "Expression of MAGE-E1, GAGE, and SOX-6 were determined by IHC in 50 paraffin blocks of glioblastoma." (PMID 33936223, 2021). "The expression of all the three CT antigens, especially MAGE-E1 and SOX-6, was high in patients with glioblastoma." (PMID 33936223, 2021). "As a result, the expression of GAGE was somewhat different from the other two CT antigens (SOX6 expression in 60% of glioblastoma was more than 30%, and MAGE-E1 expression in 70% of tumors was more than 10%)." (PMID 33936223, 2021). "Accumulated evidence indicates that several SOX members have been identified as tumor-specific antigens that can augment cytotoxic T lymphocytes (CTLs) response to kill cancer cells, including SOX2 (glioblastoma), SOX4 (lung cancer), SOX6 (glioblastoma), and SOX11 (glioblastoma)." (PMID 35267473, 2022). "Therefore, SOX-6 could be considered as an important prognostic factor for glioblastoma." (PMID 33936223, 2021). "In this study, we aimed to evaluate the expression rate of MAGE-E1, SOX-6, and GAGE, as three important CT antigens, among glioblastoma patients using the immunohistochemical (IHC) technique." (PMID 33936223, 2021).
leukemia (3 papers, 2016 to 2020). A malignant (clonal) hematologic disorder, involving hematopoietic stem cells and characterized by the presence of primitive or atypical myeloid or lymphoid cells in the bone marrow and the blood. "Here we demonstrate that SOX6 overexpressing BCR-ABL1+ B-ALL cells are unable to promote leukemia in a mouse model." (PMID 30833651, 2019). "ACSL6 gene was coexpressed with SRY (sex determining region Y)-box 6 (SOX6), Duffy blood group, chemokine receptor (DARC), and other genes involved in porphyrin-containing compound metabolic processes in leukemia cell." (PMID 27171439, 2016).
lung carcinoma (3 papers, 2020 to 2023). "The Sry‐related high‐mobility group box6 (SOX6) has been implicated in the development of cancer, but its role in lung cancer is incompletely understood." (PMID 31729835, 2020). "The precise role of SOX6 in lung cancer and its related molecular mechanisms remain to be identified." (PMID 31729835, 2020). "In contrast with the research in SOX5, studies on the role of SOX6 in lung cancer are relatively rare." (PMID 31729835, 2020). "Overexpression of SOX6 in SOX6‐transfected lung cancer cells (SOX6‐A549 and SOX6‐HCC827) was confirmed by western blot analysis." (PMID 31729835, 2020). "We used RT‐PCR to detect the expression of SOX6 mRNA in lung cancer samples." (PMID 31729835, 2020). "At present, whether the expression of SOX6 is related to the prognosis of lung cancer is not clear." (PMID 31729835, 2020).
myocardial infarction (3 papers, 2016 to 2025). Gross necrosis of the myocardium, as a result of interruption of the blood supply to the area, as in coronary thrombosis. "Studies proved that M2 macrophage-derived exosomes carry miR-1271-5p to regulate cardiac injury in acute myocardial infarction through downregulation SOX6." (PMID 34926690, 2021).
nasopharyngeal carcinoma (3 papers, 2022 to 2023). A carcinoma arising from the nasopharyngeal epithelium. "Then, we explored the prognostic value of STC2/ITGB2/SOX6 in nasopharyngeal carcinoma." (PMID 33797657, 2022). "We not only found its high expression in primary nasopharyngeal carcinoma tissues and lymph-node metastatic tissues, but also found that STC2-mediated regulation of EMT and glycolysis traits was partially realized through the modulation of ITGB2/FAK/SOX6 signaling." (PMID 33797657, 2022).
osteosarcoma (3 papers, 2020 to 2023). A usually aggressive malignant bone-forming mesenchymal neoplasm, predominantly affecting adolescents and young adults. "For example, SOX6 expression was decreased in osteosarcoma and exerted a suppressive effect on migration, invasion, and epithelial-mesenchymal transition by regulating TWIST1." (PMID 38062424, 2023). "The high sensitivity of SOX6-high expressing EwS cells toward Elesclomol appeared to be independent of proliferation under normal conditions, since the osteosarcoma cell line SAOS-2 and the SOX6-low expressing EwS cell line A673 proliferated even more than the tested SOX6-high expressing EwS cells." (PMID 32415069, 2020). "Indeed, in validation drug-response assays, Elesclomol strongly decreased viability of EwS cells with high SOX6 levels while the osteosarcoma cell line SAOS-2 and non-transformed human primary MSC line MSC-52 that exhibit low SOX6 expression levels were relatively resistant." (PMID 32415069, 2020).
chronic myeloid leukemia (2 papers, 2024). "In chronic myeloid leukemia (CML) stem cells (LSCs) resistant to imatinib, G9a was also found to be overexpressed and responsible for repressing the transcription of the tumour suppressor SRY-Box Transcription Factor 6 (SOX6)." (PMID 39703687, 2024).
Clear Cell Renal Cell Carcinoma (2 papers, 2021 to 2022). "We also investigated the clinical significance of TYROBP and SOX6 expression in patients with renal clear cell carcinoma." (PMID 36595751, 2022). "However, the specific molecular mechanism of TYROBP and SOX6 action in clear cell renal carcinoma remains unclear." (PMID 36595751, 2022). "TYROBP and SOX6 may be potential targets for diagnosing and treating renal clear cell carcinoma." (PMID 36595751, 2022).
colon carcinoma (2 papers, 2009 to 2025). "Notably, TMEM220-AS1, TMEM238L, SOX6, SMAD7, TCF7L2, and PYGL were significantly downregulated in colon cancer, whereas LINC02257, PCAT1, CASC8, and POU5F1B were significantly upregulated in colon cancer." (PMID 41144378, 2025).
cutaneous melanoma (2 papers, 2022 to 2025). A primary melanoma arising from atypical melanocytes in the skin. "TCGA analysis even confirmed SOX6 upregulation in cutaneous melanoma (SKCM)." (PMID 40866912, 2025). "The previously unknown loci were annotated to the pigmentation, cardiometabolic, cancer development/progression and immune-regulatory pathways, whilst others are known loci for cutaneous melanoma susceptibility (ATM, and SOX6 for BCC, and GPR98, and DSTYK for both BCC and SCC)." (PMID 36496446, 2022).
developmental delay (2 papers, 2020). "Although the knockdown of each of them individually had less impact on FB development than that of Sox6, the simultaneous knock-down of both resulted in a more severe developmental delay." (PMID 32107392, 2020).
gastric cancer (2 papers, 2016 to 2024). A primary or metastatic malignant neoplasm involving the stomach. "Subsequently, to assess the effect of SOX6 overexpression on PARP9 knockdown in gastric cancer cells, we first transfected AGS cells with a plasmid encoding SOX6 and verified overexpression efficiency via Western blot analysis." (PMID 39739965, 2024). "At present, the relationship between SOX6 and gastric cancer remains undetermined." (PMID 39739965, 2024). "Though the regulatory connection between miR-132-3p and FOXO1 has already been reported in gastric cancer cells, the direct targeting of miR-132-3p with GDF5 and SOX6 was newly discovered." (PMID 27556448, 2016).
liver cancer (2 papers, 2021 to 2023). An epithelial or non-epithelial malignant neoplasm that arises from the liver. "Curcumin decreases the proliferation of liver cancer cells by downregulating miR-21-5p and upregulating its target, SRY-box transcription factor 6 (SOX6)." (PMID 36612314, 2023).
lymph node metastasis (2 papers, 2020 to 2024). "Patients with poorly differentiated or lymph node metastasis often also showed down‐regulation of SOX6 expression." (PMID 31729835, 2020). "Univariate analysis revealed that low SOX6 expression (P < 0.001), poor differentiation (P < 0.001), lymph node metastasis (P < 0.001) and late disease stage (P < 0.001) were significant prognostic factors." (PMID 31729835, 2020). "We found that low SOX6 expression significantly correlated with poor differentiation (P < 0.001) and lymph node metastasis (P < 0.05)." (PMID 31729835, 2020).
psoriasis (2 papers, 2020 to 2024). An autoimmune condition characterized by red, well-delineated plaques with silvery scales that are usually on the extensor surfaces and scalp. "The present study demonstrated that lncRNA MIR181A2HG plays a key role in the proliferation of keratinocytes by regulating miR-223-3p targeting SOX6, which suggests that MIR181A2HG may be a potential diagnostic and therapeutic target for psoriasis." (PMID 38848163, 2024).
renal fibrosis (2 papers, 2024). A final common manifestation of a wide variety of chronic kidney diseases characterized by glomerulosclerosis and tubulointerstitial fibrosis. "Knockdown of XIST also inhibited apoptosis and inflammation caused by renal fibrosis in mice model by mir-19b mediated downregulation of SOX6, and several studies demonstrated XIST as a potential biomarker for diseases related to glomerular nephropathy." (PMID 40176927, 2024). "In fact, emerging evidence demonstrated that SOX6 serves as a target for a number of miRNAs in renal fibrosis such as miR-342-3p, miR-19b, and miR-185-5p." (PMID 39379100, 2024). "Several studies have shown that SRY-box transcription factor 6 (SOX6) may be a target of miR-342-3p in renal or cardiac injuries and implicate in renal fibrosis, so we sought to examine whether SOX6 plays a role for the anti-fibrosis effect of miR-342-3p during oral fibrogenesis." (PMID 39379100, 2024).
sarcoma (2 papers, 2020 to 2025). A usually aggressive malignant neoplasm of the soft tissue or bone. "Several of the identified MLS- and EWS-specific transcription factors are implicated in FET sarcoma oncogenesis; for example, increased gene expression of the EWS-specific transcription factors HOXD11, SOX6, MEIS1, and E2F6 were reported to be involved in EWS malignancy." (PMID 40988026, 2025). "The relatively high expression of SOX6 in EwS compared to other sarcomas and pediatric cancers implied that there might be a regulatory relationship with the EwS specific fusion oncogene EWSR1-FLI1." (PMID 32415069, 2020).
achondroplasia (1 paper, 2008). Achondroplasia is the most common form of chondrodysplasia, characterized by rhizomelia, exaggerated lumbar lordosis, brachydactyly, and macrocephaly with frontal bossing and midface hypoplasia. "The gain-of-function mutant of Fgfr3 causes achondroplasia, Sox9 controls chondrocyte differentiation via Sox5 and Sox6 expression, and Ihh is a master gene of bone development under BMP control, suggesting that Slc39a13 exerts a profound influence on genes crucial to chondrocyte differentiation." (PMID 18985159, 2008).
acral melanoma (1 paper, 2025). "Particularly in acral melanoma (AM), little were known for SOX6 in promoting AM progression, compared to other SOX family members like SOX4 and SOX10." (PMID 40866912, 2025).
Arthritis (1 paper, 2024). Inflammation of a joint. "In the arthritis model, the GSE plays an antioxidant property in preventing bone destruction and inflammation through increased Sox6 expression." (PMID 37311556, 2024).
atopic dermatitis (1 paper, 2024). "SOX6 is abnormally expressed in the epidermis of atopic dermatitis patients, where it impairs skin barrier development through suppressing epidermal differentiation and epigenetically silences critical genes involved in keratinocyte differentiation by recruiting SMARCA complex components." (PMID 38848163, 2024).
attention deficit-hyperactivity disorder (1 paper, 2022). A disorder characterized by a marked pattern of inattention and/or hyperactivity-impulsivity that is inconsistent with developmental level and clearly interferes with functioning in at least two settings (e.g. at home and at school). "Disruption of Sox6 exons in humans with delayed speech development and attention deficit hyperactivity disorder is associated with generalized dystonic and pectus carinatum." (PMID 36232654, 2022).
brain tumors (1 paper, 2020). "SOX6 and SOX13 could co-interact with FOXC1 and GATA2, which might lead to aggressive the brain tumors." (PMID 32388501, 2020).
cardiac arrhythmia (1 paper, 2016). Any disturbances of the normal rhythmic beating of the heart or MYOCARDIAL CONTRACTION. "Mice homozygous for a Sox6 null mutation die within two weeks after birth and presented cardiac arrhythmia." (PMID 27832192, 2016).
cartilage disease (1 paper, 2024). Softening and degeneration of the CARTILAGE. "Past research has reported that PACAP play an important role in cartilage diseases by regulating SOX family member molecules such as SOX5, SOX6, SOX9." (PMID 39619607, 2024).
Cerebral ischemia (1 paper, 2020). Restriction of arterial blood supply to the brain associated with insufficient oxygenation to support the metabolic requirements of the tissue. "Downregulated UCA1 upregulates the miR-18a, which inhibits the SRY-box containing gene 6 (SOX6) as the target gene, thus, preventing hypoxia injury following cerebral ischemia via increasing migration, invasion, and viability, and inhibiting apoptosis in neural PC-12 cells." (PMID 33321920, 2020).
Cirrhosis (1 paper, 2024). A chronic disorder of the liver in which liver tissue becomes scarred and is partially replaced by regenerative nodules and fibrotic tissue resulting in loss of liver function. "Additionally, upregulated TF activities in MYOFIB/HSC were noted for PATZ1 in preneoplastic stages (e.g., Cirrhosis, AK, and CAG), while CEBPZ and SOX6 demonstrated elevated activities in malignant (e.g., cSCC and HCC) stages." (PMID 38645221, 2024).
cyst (1 paper, 2008). A sac-like closed membranous structure that may be empty or contain fluid or amorphous material. "However, no outgrowths were observed in twenty fat pads transplanted in three independent experiments with cells carrying the Sox6-GFP, although in two cases, cyst-like GFP-labelled structures were observed." (PMID 19063729, 2008).
dilated cardiomyopathy (1 paper, 2024). Cardiomyopathy which is characterized by dilation and contractile dysfunction of the left and right ventricles. "scGO also identified CUX1, SOX6, and SVIL, which have been reported as pivotal factors implicated in causing dilated cardiomyopathy." (PMID 39820437, 2024).
Dystonia (1 paper, 2017). An abnormally increased muscular tone that causes fixed abnormal postures. "Remarkably, reminiscent of the presentation seen in our SOX5-mutated index patient, dystonia in the SOX6 deletion patient was of acute onset and combined with other hyperkinesia." (PMID 29214085, 2017).
embryonal carcinoma (1 paper, 2024). A non-seminomatous malignant germ cell tumor characterized by the presence of large germ cells with abundant cytoplasm resembling epithelial cells, geographic necrosis, high mitotic activity, and pseudoglandular and pseudopapillary structures formation. "Scrambling the first SOX site consistently reduced L1.3 retrotransposition efficiency by ~50%, in HeLa cells with and without stable SOX6 overexpression and in cultured PA-1 embryonal carcinoma cells." (PMID 38773348, 2024).